TSPO (translocator protein)
Diseases named in the same sentence as TSPO in open-access papers (continued):
Sharing a sentence is not in itself a finding about the gene and the disease.
psychosis (18 papers, 2017 to 2025). "The TSPO-associated neuroticism trait indicates an unexplored connection between neuroimmune activation and personality that varies across the psychosis spectrum." (PMID 33354652, 2020). "This study aimed to investigate the association between personality and TSPO expression across the psychosis spectrum." (PMID 33354652, 2020). "To conclude, the low reliability and sensitivity of (R)-[11C]PK11195 outcomes used to examine TSPO in psychosis, caused by both radioligand characteristics and quantification methods, clearly limits the informational value of these studies." (PMID 30739609, 2019). "In this study, for the first time, we aim to investigate whether personality traits are linked to TSPO expression across the spectrum of HVs, psychosis risk, and psychosis." (PMID 33354652, 2020). "The primary aim of this study was to investigate whether personality traits are linked to TSPO expression, a neuroimmune marker, in the spectrum from health to psychosis and psychosis risk." (PMID 33354652, 2020). "Our findings therefore add to an emerging body of evidence that TSPO availability is reduced in the early years of psychosis and possibly especially apparent in drug-free patients." (PMID 32606376, 2021). "Even though a direct neuronal contribution to altered TSPO expression or binding in psychosis still awaits verification, these findings are in line with the notion that glial cells are unlikely to be the sole cellular sources underlying these changes." (PMID 32398717, 2021). "Remarkably, this interaction between age- and state-dependent effects appears to mimic our earlier findings of an interaction between age and psychotic state in a longitudinal TSPO PET study in patients with psychotic disorders." (PMID 34339805, 2021). "Both increased, unchanged, and decreased brain TSPO measures have been reported in patients with psychosis with different directions of effect seemingly depending on the properties of used radiotracers." (PMID 32179746, 2020). "This analysis sought to resolve some of the methodological issues of prior work with improved power, revealing significantly lower TSPO across the brain of individuals with early psychosis." (PMID 33354652, 2020). "Combining TSPO PET imaging with proton magnetic resonance spectroscopy further revealed a positive association between TSPO binding and the levels of γ-aminobutyric acid (GABA) in the mPFC of people at clinical high risk for psychosis and healthy volunteers." (PMID 32398717, 2021). "Moreover, we have recently demonstrated important age effects on microglial activity during psychosis in a subpopulation of our current sample, in whom TSPO radioligand uptake was measured using Positron Emission Tomography." (PMID 32010121, 2019). "In fact, given our findings presented here, the prefrontal downregulation of TSPO occurring in a subset of patients with psychotic disorders and in disease-relevant animal models may, at least in part, reflect reduced neuronal activity in PFC structures or “hypofrontality”." (PMID 32398717, 2021). "The 18-kDa translocator protein (TSPO), a suggested marker for brain microglial cell activation, has been widely studied with positron emission tomography (PET) in psychotic disorders to test the microglial hypothesis of schizophrenia." (PMID 32179746, 2020). "As described in patients at risk of psychosis, in this group of patients with FEP, the results are conflicting, with three main studies describing an increase, a decrease or the absence of changes in TSPO tracing." (PMID 36443303, 2022). "Heterogeneity seems to come with the territory of psychiatry, and the study of positron emission tomography (PET) imaging of immune alterations in the central nervous system using nuclear ligands targeting translocator protein 18 kDA (TSPO) in psychotic disorders is no different." (PMID 32425835, 2020).
cognitive decline (16 papers, 2016 to 2026). "For example, translocator protein (TSPO) PET imaging has been employed to detect central neuroinflammatory activity associated with postoperative cognitive decline in elderly patients." (PMID 40843245, 2025). "Equally, several TSPO PET studies have found that higher TSPO PET binding was associated with steeper cognitive decline over time." (PMID 41272848, 2025). "In vivo TSPO radioligand binding is increased in AD patients compared to controls, and this increased uptake is associated with worsening cognitive decline." (PMID 39540994, 2024). "Post-mortem and in vivo TSPO measurements of AD brains have shown greater TSPO density in later stages of AD, correlating AD-associated cognitive decline with microglial activation." (PMID 33854417, 2021). "In vivo cerebral metabolism and TSPO signals indicate that obesity can accelerate amyloid-induced inflammation and associated cognitive decline." (PMID 27578213, 2016). "We hypothesized that [11C]PK11195 binding would predict longitudinal long-term cognition and survival, where higher TSPO PET binding would be associated with faster cognitive decline and higher mortality in MCI and AD dementia." (PMID 41272848, 2025). "Based on our results, we posit that the dynamic interplay between the activated glia-mediated immune responses through the TSPO mechanism underpins the cognitive decline observed in meningitis survivors." (PMID 31901235, 2020). "However, a high level of TSPO expression seems to be indicative of a possible early protective phenotype, reflected by a high initial binding leading to a slower cognitive decline and vice versa." (PMID 39540994, 2024). "Whilst this is the first study examining TSPO expression after ionizing radiation exposure, several studies have demonstrated microglial activation after high dose ionizing radiation exposure, often leading to cognitive decline." (PMID 34760884, 2021). "In this context, we hypothesize that persistent microglial activation and perpetuated levels of TSPO expression might play a role in cognitive decline in meningitis survivors." (PMID 31901235, 2020). "Animals showed a cognitive decline in all tasks compared with the control group, and this impairment may be at least partially mediated by activating a glia-mediated immune response and upregulating TSPO." (PMID 31901235, 2020). "Thus, we hypothesize that persistent microglial activation followed by TSPO-mediated neuroinflammation might play a role in the long-term cognitive decline exhibited in meningitis animals." (PMID 31901235, 2020). "CTx is suspected to elevate inflammatory cytokine levels, possibly detected by FDG-PET, decrease dopamine release, measurable by TRODAT-SPECT, or directly by TSPO-PET through microglia and astrocyte, all mechanisms possibly contributing to cognitive decline." (PMID 34919195, 2022). "In a study using a second-generation TSPO tracer, [11C]DPA-713 BPND was found to be the best predictor of decline in global cognition and memory in MCI and AD dementia patients, where again higher PET signal was related to steeper cognitive decline." (PMID 41272848, 2025). "As such, a future study using TSPO-PET to longitudinally assess neuroinflammation in these MDX murine models—alongside cognitive testing—is suggested to better delineate the relationship between early neuroinflammation and late-onset cognitive decline." (PMID 37108685, 2023). "Furthermore, an examination of clinical progression of AD found that TSPO and tau PET together were the best predictors of disease progression and cognitive decline." (PMID 37580767, 2023).
Obesity (16 papers, 2011 to 2026). Accumulation of substantial excess body fat. "In summary, our findings indicate that obesity is linked to high TSPO expression specifically in females with AD, which implies that high TSPO-PET levels deserve distinct interpretation among sexes." (PMID 38263017, 2024). "We investigated whether neuroinflammation (TSPO availability) and brain activity drive the obesity‐associated increase in BGU and whether this increase is reversed by exercise training." (PMID 40926735, 2025). "Furthermore, sex moderates the association between obesity and microglial activation, speaking for a dependence of obesity related TSPO enhancement from features that are present in females, as for example elevated tau." (PMID 38263017, 2024). "Sex and obesity effects on TSPO-PET binding have been reported for cognitively normal humans (CN), but such effects have not yet been systematically evaluated in patients with AD." (PMID 38263017, 2024). "Despite the neuroinflammatory pathogenesis of diet-induced obesity, and the translational potential of targeting TSPO, there is sparse literature characterizing the effect of TSPO on appetite." (PMID 34343461, 2021). "The increased level of TSPO has been observed in neurodegenerative diseases and disorders, brain injury, and cancer, while the dysregulation of TSPO has been detected in obesity and diabetes." (PMID 34212002, 2021). "Although our results support an involvement of TSPO in obesity, we cannot determine if this effect is related to brain TSPO expression specifically or if this is reflective of systemic differences." (PMID 31363804, 2019). "Taken together, further studies on the role of TSPO and neuroinflammation in obesity are warranted to address these questions." (PMID 31363804, 2019). "We also found that the modulation of mitochondrial fatty acid oxidation is a demonstrated function of TSPO and an anti-obesity intervention." (PMID 28346358, 2017). "Obesity combined with Aβ infusion was found to increase both TSPO-PET signals and cerebral glucose metabolism." (PMID 27578213, 2016). "Because TSPO is a mitochondrial protein with many functions, it may be speculated that obesity decreases mitochondrial content or functional properties also in the brain." (PMID 40926735, 2025). "The translocator protein of 18 kDa (TSPO) is a modulator of neuroinflammation that may also regulate diet-induced obesity." (PMID 34343461, 2021). "RIM-BP1's association with obesity, binding to TSPO and predominate expression in the limbic system suggest that RIM-BP1 may modulate TSPO's role in appetite regulation." (PMID 34343461, 2021). "Thus, the statistical power was not sufficient to include several covariates that have been shown to be associated with TSPO-PET binding, such as obesity." (PMID 34073557, 2021). "TSPO expression is altered by obesity in a tissue‐dependent manner." (PMID 34423477, 2021). "Prior work from our group and others has shown that, in rodents, TSPO levels are altered in adipose tissue by obesity and that modulation of TSPO activity may impact systemic glucose homeostasis." (PMID 34423477, 2021). "By building on these foundational findings, future research may identify a strategy to target TSPO as an obesity treatment." (PMID 34343461, 2021). "TSPO expression in adipose tissues is reduced in obesity as well as in the placenta of obese women." (PMID 28346358, 2017). "Serum levels of numerous obesity-linked chemokines promoting adipocyte proliferation (TIMP-1) and adipose macrophage infiltration (CXCL1, CXCL2, CXCL12, CCL3, and CCL5) were found to be significant predictors of in vivo hippocampal TSPO signals." (PMID 27578213, 2016). "Therefore, TSPO may represent a therapeutically viable target for the treatment of diet-induced obesity." (PMID 34343461, 2021).
Obesity (continued). "Immunohistochemical data from this study suggested that, within adipose tissue of obese animals, TSPO levels may be decreased in adipocytes but increased in adipose tissue macrophages within “crown‐like” structures, which, during obesity, are predominantly of a pro‐inflammatory phenotype." (PMID 34423477, 2021). "The increase in pancreatic expression of TSPO noted here, therefore, could impact on the cholesterol efflux pathway or exert a number of other protective effects sustaining pancreatic function under the challenge of genetic obesity, which could be explored in future studies." (PMID 30819824, 2019). "While not a cell surface antigen, a lack of TSPO expression, a drug target for diabetes and obesity, was observed to uniquely characterize undifferentiated NP88 and NP110 progenitors." (PMID 30616682, 2019). "Obesity can alter the whole body distribution of 11C-PBR-28; therefore, the brain uptake expressed as %ID/g may result in an underestimation of TSPO signals in obese groups." (PMID 27578213, 2016). "However, how TSPO regulates appetite in diet-induced neuroinflammatory obesity is not widely discussed." (PMID 34343461, 2021). "However, the magnitude and duration of the Aβ-induced inflammatory response was exacerbated by obesity, even though obesity alone did not increase TSPO inflammatory signals." (PMID 27578213, 2016).
tauopathy (16 papers, 2018 to 2025). Neurodegenerative disorders involving deposition of abnormal tau protein isoforms (tau proteins) in neurons and glial cells in the brain. "Regional accumulation of tau was the strongest predictor of microglial activation in individual patients with primary and secondary tauopathies, whereas Aβ, perfusion, and gray matter volumes indicated only weaker associations with regional TSPO-PET." (PMID 37495886, 2023). "The parallel changes of TSPO densities and tau fibrils provide a better understanding of how microglia are implicated in tauopathy." (PMID 32842621, 2020). "We used PSP as a demonstrator tauopathy because of its high clinicopathological correlation, prognostic relevance of increased TSPO radioligand binding, and short disease course with a short timeframe between PET and death." (PMID 40036275, 2025). "This supports the interpretation of TSPO PET as a microglia-specific neuroinflammatory biomarker in the primary tauopathy PSP." (PMID 40036275, 2025). "In summary, our findings support the use of TSPO PET as a microglia-specific neuroinflammatory biomarker in the primary tauopathy of PSP." (PMID 40036275, 2025). "The observed sex-related differences in TSPO expression have potential impact when considering novel immunomodulatory therapies, since TSPO-PET signals predicted disease progression in 4-repeat tauopathies and AD." (PMID 38263017, 2024). "We investigated a cohort of 55 patients with AD and primary tauopathies and 10 healthy controls that underwent TSPO-, Aβ-, tau-, and perfusion-surrogate-PET, as well as structural MRI." (PMID 37495886, 2023). "We also investigated TSPO expression in a model of tauopathy, TAUP301S mice, which develop tangle-like inclusions in the brain parenchyma associated with microgliosis and astrocytosis." (PMID 37640701, 2023). "Several TSPO radioligands allow monitoring neuroinflammation in AD and 4R-tauopathies and we were able to show that [18F]GE-180 recapitulates the expected topology of microglial activation in 4RTs and AD." (PMID 37495886, 2023). "Recent in vivo imaging studies with TSPO-PET demonstrated increased TSPO signals in both human tauopathies and mouse models." (PMID 33644757, 2021). "We demonstrated longitudinal in vivo monitoring of tau pathology and TSPO accumulation in tauopathy models, PS19 and rTg4510 mice, using small-animal PET imaging." (PMID 33644757, 2021). "The present study revealed that immunoreactivity of P2Y12R was regressed in tauopathy mouse models before massive accumulations of intraneuronal tau deposits and an elevation of TSPO immunoreactivity." (PMID 33644757, 2021). "To test the correlations of microglia dystrophy and tauopathy, we quantified translocator protein (TSPO) and tau fibrils using autoradiography." (PMID 32842621, 2020). "Confirmation of these hypotheses would support the interpretation of TSPO PET (specifically 11C-PK11195) as a microglial neuroinflammatory biomarker in primary tauopathies." (PMID 40036275, 2025). "Inflammation is a critical player in the progression of neurodegeneration in tauopathies; activation of microglia and astrocytes has been observed in post‐mortem studies, and is predictive of cognitive decline in longitudinal TSPO PET analyses of tauopathy cases." (PMID 40420510, 2025). "It is evident that inflammation plays a main role in neuronal loss, and maybe the use of a TSPO PET represents a valid choice in the detection and treatment response evaluation of tauopathies." (PMID 37238166, 2023). "To further investigate the temporal change of microglial phenotype during the development of tauopathy, we examined the morphological and molecular characteristics by using antibodies against several microglial markers (e.g. Iba1, TSPO, P2Y12R) in rTg4510 brains." (PMID 33644757, 2021).